CFAP73 (cilia and flagella associated protein 73)
Description:
May play a role in ciliary/flagellar motility by regulating the assembly and the activity of axonemal inner dynein arm.
Synonyms: CCDC42B; MIA2
Tractability: Small molecule: a structure with a bound ligand is known.
Gene: Protein-coding gene on chromosome 12 (113,149,716 to 113,159,526, forward strand). Ensembl gene ENSG00000186710.
Subcellular location: Cytoplasm, cytoskeleton, cilium axoneme
Subcellular location (Human Protein Atlas): Nucleoli fibrillar center; Nucleoplasm; Vesicles
Gene Ontology:
Molecular function: dynein complex binding
Biological process: cilium movement; inner dynein arm assembly
Cellular component: axonemal doublet microtubule; motile cilium; axoneme; cytoskeleton
Genetic constraint (gnomAD): Loss-of-function variants: 33 observed, 32.58 expected, observed/expected ratio (o/e) 1.01, 90% interval 0.77 to 1.35. The upper end of that interval is the gene's LOEUF score, 1.35, which puts it in group 5 of 6, group 1 being the genes least tolerant of losing a copy. Missense variants: 391 observed, 357.3 expected, observed/expected ratio (o/e) 1.09, 90% interval 1.01 to 1.19. Synonymous variants: 162 observed, 155.84 expected, observed/expected ratio (o/e) 1.04, 90% interval 0.91 to 1.18.
Homologues: Orthologues: chimpanzee CFAP73 (99% identical), macaque CFAP73 (90% identical), pig CFAP73 (79% identical), dog CFAP73 (74% identical), mouse Cfap73 (55% identical), rat Cfap73 (50% identical), tropical clawed frog cfap73 (42% identical), zebrafish cfap73 (27% identical). Paralogues in human: CCDC42 (35% identical), CCDC38 (19% identical), CFAP100 (18% identical).